IL6 (interleukin 6)
Diseases named in the same sentence as IL6 in open-access papers (continued):
Sharing a sentence is not in itself a finding about the gene and the disease.
COVID-19 (continued). "Because of these complexities, an indication for the use of drugs that neutralize IL-6 activity in COVID-19 will depend upon the results from controlled trials." (PMID 32629875, 2020). "Recent clinical studies have found that COVID-19 patients with severe illness had elevated levels of certain cytokines including IL-6, TNF-α, IL-10, MCP-1 and IP-10." (PMID 33284859, 2020). "Elevated innate immune cytokines detected in peripheral blood including interleukin (IL)-1, IL-6, IL-8, or C-X-C Motif Chemokine Ligand 10 (CXCL10) have been associated with severe or fatal COVID-19." (PMID 33010815, 2020). "Although CRP is a nonspecific marker, it becomes more specific to bioactivity of IL-6 and formation of a cytokine storm in patients with severe COVID-19." (PMID 32876941, 2020). "A further IL-6 increase in COVID-19 diabetic patients can exacerbate insulin resistance by inhibiting the autophosphorylation of the insulin receptor and the activation of PI3K and AKT pathway." (PMID 33312199, 2020). "This systematic review and meta-analysis aimed to assess the safety and efficacy of anti-IL-6 signaling (anti-IL6/IL-6R/JAK) agents on COVID-19 based on the current evidence." (PMID 33384605, 2020). "Extended populations of IL-6 and IL-1β secreting monocytes have been found in COVID-19 infected patients, resulting in elevated serum IL-6 and lactate dehydrogenase, a marker of pyroptosis, a highly inflammatory form of programmed cell death." (PMID 33133071, 2020). "Within COVID-19 patients, serum IL-6 and IL-10 levels are significantly higher in critical group (n = 17) than in moderate (n = 42) and severe (n = 43) group." (PMID 32475230, 2020). "The drivers of inflammation and lymphocytopenia in COVID-19 are not well understood yet, but the preliminary data generated to date by this and other studies suggest that interfering with IL-6 activity improves these indices." (PMID 33089038, 2020). "Patients with COVID-19 show high plasma levels of IL-6, which correlate with disease severity and multiorgan failure." (PMID 33033405, 2020). "Although increase vascular permeability resulting in plasma leakage and shock is the main pathological feature of DHF, IL-6 appears to contribute less to disease pathogenesis of DHF compared to COVID-19." (PMID 33199778, 2020). "More severe COVID-19 cases are frequently accompanied by laboratory and immunologic changes like C-reactive protein increases, lymphopenia and interleukin (IL)-6 peaks." (PMID 32443442, 2020). "While both moderate and severe COVID-19 present with an increase in IL-6, concentrations ≥100 pg/mL are observed exclusively in critically ill patients with high systemic viral nucleic acid detection." (PMID 33505321, 2020). "Soluble interleukin-2 receptor (sIL-2R) and interleukin-6 (IL-6) were significantly increased in patients with severe COVID-19." (PMID 33194697, 2020). "At present, blockers of IL-6/IL-6R have been preliminarily applied in a series of ongoing clinical trials of COVID-19 and further multi-center clinical trials are being carried out." (PMID 33329533, 2020). "Increased levels of inflammatory cytokines such as tumor necrosis factor-alpha, interleukin-1, interleukin-6, and interleukin-10 are found in patients with severe COVID-19." (PMID 33133323, 2020). "Interleukin 6 (IL-6) was elevated in total COVID-19 patients as well as in the severe group, while IL-10 was increased only in severe cases." (PMID 32669467, 2020). "Severe COVID-19 can be accompanied by an important IL-6 increase, like previous emerged coronaviruses." (PMID 32748880, 2020). "Whereas the two patients with agammaglobulinemia had a benign COVID-19 course, the five patients with CVIDs presented with a severe form of COVID-19, requiring treatment with multiple drugs, including IL-6–blocking drugs and mechanical ventilation." (PMID 33335532, 2020).
COVID-19 (continued). "We next examined expression of IL-6 protein by immune cells in the blood of COVID-19 patient since the production of this cytokine is known to be increased by BTK activity in normal human monocytes/macrophages." (PMID 32503877, 2020). "A recent retrospective, multicenter study of 150 confirmed COVID-19 cases revealed that elevated IL-6 was a predictor of mortality, indicating that IL-6 played a central role in the hyperinflammation and CRS in the critical patients." (PMID 33195318, 2020). "As a whole, the levels of IL-6 and IL-10 were significantly higher in severe COVID-19 from our results, suggesting a more serious cytokine storm underlying the pathogenesis of COVID-19." (PMID 33552062, 2020). "Measurement of ferritin and C-reactive protein, as well as quantification of interleukin-6 on indication, should be performed in patients with severe COVID-19." (PMID 33054818, 2020). "Among these cytokines, IL-6 is a key mediator for the development of cytokine storm in COVID-19 cases." (PMID 32712629, 2020). "Nevertheless, a case report found no beneficial therapeutic effect of tocilizumab on one severe COVID-19 patient with low pretreatment plasma IL-6 (74.3 pg/mL), who developed viral myocarditis and lymphopenia after receiving tocilizumab treatment." (PMID 33584679, 2020). "There were modest elevations in plasma IL-6 in COVID-19 patients, with only 6 patients reaching IL-6 concentrations greater than 1000 pg/μL, as typically seen during overwhelming bacterial sepsis or cytokine release syndrome." (PMID 32687484, 2020). "Nevertheless, it is the first report highlighting the ability of itolizumab reducing circulating IL-6 in severe COVID-19 patients." (PMID 33292350, 2020). "Analysis of COVID-19 patients revealed that IL-2, IL-6, IL-7, IL-10, granulocyte stimulating factor, interferon γ inducible protein 10, monocyte chemoattractant protein 1, macrophage inflammatory protein 1-α, and tumor necrosis factor α were increased." (PMID 32948238, 2020). "Based on these findings, anti-IL-6 or IL-1 treatment was carried out in COVID-19 and showed significant improvement in the patients’ symptoms." (PMID 32834892, 2020). "Early reports argue that lower levels of IL-6 were observed in severe COVID-19, inconsistent with a true cytokine storm." (PMID 33303843, 2020). "Severely ill patients with COVID-19 have a high level of pro-inflammatory cytokines, such as IL-6, compared to patients with moderate symptoms." (PMID 33207753, 2020). "It has recently been shown that interleukin-6 (IL-6) was also expressed significantly higher in patients who succumbed to coronavirus disease 2019 (COVID-19) than in survivors." (PMID 32321823, 2020). "Anti-IL-6, as a drug targeting cytokine pathway and based on its mechanism of action, has potential benefits in COVID-19-related ARDS and pneumonia." (PMID 32723362, 2020). "IL-6 concentration is thus a reliable predictor of COVID-19 severity as it is significantly elevated in fatal cases." (PMID 33194450, 2020). "Higher plasma levels of cytokines, including interleukin (IL)-6, IL-2, IL-7, IL-10, and tumor necrosis factor-α, were found in patients with COVID-19, which implies the occurrence of a cytokine storm and its association with disease severity." (PMID 33335906, 2020). "COVID-19 patients exhibit abnormal immune responses related to high levels of proinflammatory cytokines, including TNFα and IL-6." (PMID 32708495, 2020). "Multivariate logistic regression analysis revealed that IL-6 > 50 pg/mL and LDH > 400 U/L on admission were independently associated with disease severity in patients with COVID-19." (PMID 32854750, 2020). "Acute phase proteins such as CRP, LDH, ferritin, procalcitonin, D-Dimer, ESR and IL-6 have also been well correlated with the disease severity, progression and poor outcome in COVID-19." (PMID 33225909, 2020). "Question 17: Should interleukin-6 inhibitors be used to treat COVID-19 patients to improve clinical outcomes?" (PMID 32887670, 2020).
COVID-19 (continued). "In a small study of COVID-19 patients, a combination of IL-6 levels > 80 pg/mL and CRP levels > 97 mg/L were highly predictive of the need for mechanical ventilation." (PMID 32922297, 2020). "Other studies showed elevated levels of IL-6 in COVID-19 patients, and the serum IL-6 level was significantly higher in patients with severe disease than in those without severe disease (108 ± 12 ng/L vs 34 ± 7 ng/L)." (PMID 33240265, 2020). "IL-6 is a fundamental factor of the cytokine storm in patients with severe COVID-19, where it is responsible for the fatal outcome of the disease." (PMID 33114676, 2020). "We therefore examined the concentrations of serum cytokines, including TNF-α, IFN-γ, IL-2, IL-4, IL-6, and IL-10, from these COVID-19 patients to explore the influence of cytokine signaling." (PMID 32425950, 2020). "Clear examples are anti-IL-6 compounds for patients with severe forms of COVID-19 and hydroxychloroquine, widely used and highly questioned." (PMID 33519443, 2020). "As such, the role of a cytokine storm wherein IL-6 is considered to be highly involved in the pathogenesis of COVID-19 warrants further exploration." (PMID 33584679, 2020). "Our results also demonstrated that severe COVID-19 patients had higher concentrations of IL-6, IL-8, IL-2,TNF-α, and IFN-γ in the serum than mild case patients, which suggested that the magnitude of cytokine storm was associated with the disease severity." (PMID 32484453, 2020). "Other drugs borrowed by the “rheumatological world” have been used in COVID-19 because of their anti-inflammatory power: tocilizumab, an anti-IL6 antibody; anakinra, an anti-IL1 antibody; and baricitinib, an anti-JAK1 compound." (PMID 33014780, 2020). "A correlation between the serum levels of interleukin-6 (IL-6) and the severity of COVID-19 symptoms has been reported." (PMID 33195321, 2020). "Intriguingly, only IL-6 as a key factor that triggered the cytokine storm in COVID-19 patients was activated in low calcium cases in both mild/moderate and severe/critical groups." (PMID 33252122, 2020). "For instance, both ascarid and hookworm infections appear to reduce IL-6 and TNF-α, elevated levels of which have been associated with increased COVID-19 severity." (PMID 33235797, 2020). "Another study including 21 COVID-19 cases reported that severe cases had increased IL-2R, IL-6, IL-10, and TNF-α when compared to moderate cases." (PMID 32727465, 2020). "Cytokine release syndrome (CRS) induced by elevated interleukin-6 was recognized to underscore the pathology of severe COVID-19 patients." (PMID 33195318, 2020). "The improvement of patient health and the modest side effects suggest the use of IL-6 antagonist therapy not only against COVID-19 but also in the treatment of other lethal viruses." (PMID 32847008, 2020). "We designed a trial testing tocilizumab versus standard of care intending to improve the outcomes by inhibiting interleukin-6, an important inflammatory mediator in COVID-19." (PMID 32965395, 2020). "More recently, a study found that the IFN-I responses are abrogated in peripheral blood from severe COVID-19 patients, a contrast to the high IL-6 and TNFα levels observed." (PMID 33377937, 2020). "Of these cytokines, IL-6 has been identified as one of the most important pro-inflammatory mediators in COVID-19." (PMID 33138181, 2020). "Making use of IL-6, COVID-19 expands Th17 cells which provide antibacterial protection, but are also associated with the development of autoimmune diseases." (PMID 33361522, 2020). "In COVID-19 patients, elevated levels of IL-6 were associated with significant upregulation of P-selectin and PSGL-1, suggesting that IL-6 may exacerbate immune thrombosis by promoting platelet-leukocyte aggregation and endothelial activation." (PMID 41601490, 2026). "Typically, in severe cases of COVID-19, elevated interleukin-6 (IL-6) levels are common." (PMID 40158620, 2026).
COVID-19 (continued). "We evaluated a biomarker-based risk stratification model, the Composite COVID-19 Biomarker Risk (CCBR) score, integrating age and inflammatory biomarkers (IL-6, PAI-1, LDH, neutrophil-to-lymphocyte ratio [NLR], and ferritin) measured at hospital admission to support early clinical risk assessment." (PMID 42193399, 2026). "The phenomenon of a cytokine storm – originally characterized in acute severe COVID-19 – refers to an excessive and uncontrolled release of pro-inflammatory cytokines, including interleukin-6 (IL-6), tumor necrosis factor-alpha (TNF-α), and interleukin-1 beta (IL-1β)." (PMID 41497070, 2026). "This supports the hypothesis that IL-6 may be a mechanistic biomarker of COVID-19 sequelae and that acute COVID-19 severity may mediate this relationship." (PMID 41822694, 2026). "Thus, IL-6 and GM-CSF have a central role in COVID-19, with GM-CSF more highly dysregulated than in influenza virus infection." (PMID 41516418, 2026). "Other inflammatory cytokines such as IL-1β, IL-4, IL-2, IL-10, and TNFα have also been found to increase, with IL-6 and TNFα still increased in patients with a neurological symptom profile, and IL-1β was upregulated in patients with persistent COVID-19 symptoms." (PMID 41516418, 2026). "At the other end of the spectrum, optimal vitamin D levels could contribute to the reduction of inflammatory reactions mediated by interleukin-6 (IL-6) and interferon gamma (IFNγ), which are predictors of a poor prognosis in severe cases of COVID-19." (PMID 40427060, 2025). "In this single-center cohort of moderate-to-severe COVID-19, we evaluated whether early changes in the inflammatory balance between IL-6 and IL-10 were summarized by the DBS-track short-term clinical trajectory." (PMID 41322840, 2025). "The pathophysiology of COVID-19 involves a series of complex events that occur in the body in response to infection by the virus, such as the inflammatory response, which involves release of proinflammatory cytokines including interleukin-6 (IL-6)." (PMID 40115432, 2025). "Indeed, COVID-19 triggers a hyperinflammatory response—also known as a cytokine storm—which is marked by elevated levels of pro-inflammatory cytokines such as IL-6, TNF-α, and IL-1β." (PMID 40217761, 2025). "However, this is consistent with the clinical natural course of cytokine storms (represented by IL-6) triggered by SARS-CoV-2 infection, and COVID-19-associated ALI/ARDS." (PMID 39928621, 2025). "Of the cases of PI in COVID-19 reported, many were treated with IL-6 inhibitors." (PMID 40062180, 2025). "Finally, the only randomized controlled trial to exist for IL-17 inhibition as treatment for COVID-19 looked at the use of ixekizumab, low-dose IL-2, or colchicine (an indirect IL-6 inhibitor) compared to standard of care in 60 participants." (PMID 40333142, 2025). "Notably, not just HOCl itself, but also its derivative N-chlorotaurine (NCT) is able to downregulate IL-6-dependent pro-inflammatory pathways, which play an important role in clinical conditions like those seen with severe COVID-19." (PMID 41012647, 2025). "Some suspect that the IL-6 inhibitor used to treat COVID-19 might be responsible for the PI cases seen in COVID-19 patients." (PMID 40062180, 2025). "Accelerated fibrosis: COVID-19-induced alveolar injury and cytokine storms (e.g., IL-6, TNF-α) may synergize with silica/coal dust to accelerate pulmonary fibrosis." (PMID 40337738, 2025). "IL-6 and TNF are well-established mediators of acute inflammation, typically upregulated in response to viral infection and often associated with disease severity in COVID-19." (PMID 41007691, 2025). "IL-6 dysregulation may result in hyperinflammation that is characteristic of severe COVID-19, particularly in patients requiring intensive care." (PMID 40489562, 2025).
COVID-19 (continued). "Notably, elevated levels of PCT and IL-6 have been recognized as key indicators of severe COVID-19 outcomes, highlighting the need for further investigation into their significance in co-infected patients." (PMID 40283612, 2025). "The inflammatory molecular pathways of IL-6 could also suggest an important correlation between COVID-19 and the main pediatric comorbidities, such as asthma and obesity." (PMID 40559430, 2025). "Upper-airway-related symptoms are commonly observed in patients with both COVID-19 and Self-RPD+, potentially representing the primary mechanism responsible for sustaining elevated IL-6 levels in this group, compared to patients with COVID-19 alone, Self-RPD+ alone, or healthy controls." (PMID 40647649, 2025). "This is also the reason why COVID-19 is treated with the anti-IL-6 monoclonal antibody tocilizumab." (PMID 40722786, 2025). "In addition to IL-6, several other biomarkers are routinely monitored in severe COVID-19 and viral sepsis." (PMID 41517263, 2025). "The analysis of the non-COVID-19 cohort showed several significant correlations: AST was positively associated with troponin I, CRP, IL-6, and D-Dimer; creatinine with IL-6 and platelets; and GFR with GGT, while GFR was negatively correlated with IL-6." (PMID 40364223, 2025). "Moreover, a reduction of IL-6 in hospitalized patients with COVID-19 following both remdesivir and corticosteroid administration has been reported." (PMID 40124495, 2025). "IL-6 secretion levels were higher in COVID-19 deaths than in survivors, suggesting that COVID-19 mortality may be due to a virus-activated cytokine storm including IL-6." (PMID 40872607, 2025). "A retrospective, multicentric study has identified elevated ferritin and interleukin 6 levels, which may be a predictor of mortality among COVID-19-infected patients." (PMID 40430138, 2025). "The principal component analysis revealed that the log IL-6/KL-6 ratio was linearly related to automatically-determined ground glass volume on lung CT and may therefore be predictive of lung involvement in COVID-19." (PMID 40397955, 2025). "Meanwhile, elevated concentrations of IL-6 have been consistently documented in individuals with COVID-19, including during gestation, and function as an indicator of maternal immune activation, a process that has been implicated in the developmental origins of schizophrenia in offspring." (PMID 40806558, 2025). "Indeed, in the patients with COVID-19, IL-6 levels were elevated, suggesting hyperactivation of the humoral immune response." (PMID 40005354, 2025). "In COVID-19 patients, IL-6 has been shown to drive T cell death, contributing to lymphopenia." (PMID 40724799, 2025). "IL-6 and IL-8 are key inflammatory cytokines elevated in severe COVID-19, suggesting that increased TIMP-2 and AAT may protect tissues from proteolytic damage." (PMID 40557167, 2025). "The age-dependent strength of the IL-6 amplifier’s feedback loop may correspond with the age-dependent increase in COVID-19 morbidity and mortality." (PMID 40552181, 2025). "In addition, the study highlighted the therapeutic abilities of IL-6 inhibitors, including siltuximab and tocilizumab, in addressing autoimmune diseases, cytokine release syndrome, and hyperinflammation induced by COVID-19." (PMID 39996755, 2025). "Profiling serum samples from COVID-19 patients of varying severity showed strong correlations between metabolites and pro-inflammatory cytokines/chemokines, including IL-6 and IL-1β, highlighting a regulatory interplay between arginine, tryptophan, purine metabolism, and hyperinflammation." (PMID 41002992, 2025). "Furthermore, the Immunomodulators used for the treatment of COVID-19 are antibodies that usually target IL-6, IL-6R, and other interleukins that are also components of the cytokine storm." (PMID 40149530, 2025).